LDHA (lactate dehydrogenase A)
Diseases named in the same sentence as LDHA in open-access papers (continued):
Sharing a sentence is not in itself a finding about the gene and the disease.
lung carcinoma (continued). "The differential expression patterns of LDHA and LDHB in lung cancer suggest their potential as prognostic biomarkers." (PMID 41154605, 2025). "The results showed PLK1, LDHA, FURIN, FSCN1, and RAB27B were up-regulated in lung cancer tissues, and MS4A1 was down-regulated in lung cancer tissues." (PMID 37604869, 2023). "Concluding our investigation, qRT-PCR experiments confirmed the heightened expression levels of EPHX1, LDHA, SHC1, MYO6, and TLE1 in lung cancer cell lines." (PMID 37965333, 2023). "It was reported that several oncogenic tyrosine kinases phosphorylated LDHA at Y10 in various cancers, such as FGFR1 in lung cancer, BCR-Abl in chronic myelogenous leukemia, and JAK2 in human erythroleukemia." (PMID 35525866, 2022). "Previous studies have reported that NDUFA4 promotes the progression of lung cancer cells via activating PI3K/AKT pathway and the PI3K/AKT pathway is responsible for glycolysis by regulating HIF-1α target genes ENO1 and LDHA." (PMID 35977935, 2022). "The overexpressed PKM2 and TRIB2 increased the expression of GLUT1, LDHA, and PTBP1 to promote the aerobic glycolysis in lung cancer cells." (PMID 35790734, 2022). "As a result, LDHA and GLUT1 promote the aerobic glycolysis to provide energy for TRIB2-treated lung cancer cells." (PMID 35790734, 2022). "It has been reported that several oncogenic tyrosine kinases phosphorylated LDHA at Y10 in various cancers, such as FGFR1 in lung cancer, BCR-Abl in chronic myelogenous leukemia, and JAK2 in human erythroleukemia." (PMID 35525866, 2022). "In clinical lung cancer specimens, DSTYK protein level was inversely correlated with the expression of β-catenin and LDHA." (PMID 34853310, 2021). "All data together indicated that the downregulation of c-Myc, HK2, PKM2, LDHA, PHGDH, PSAT1, cyclin D1, and CDK6 in lung cancer cells was related to the ubiquitin-protein degradation pathway, which was the result that the USP28 was inhibited by SGH." (PMID 33572615, 2021). "The protein expression levels of ALDOA, ENTPD2, LDHA, TYMS and CAT were investigated in 5 lung cancer cell lines (A549, H460, H1299, H1975, PC9), normal airway epithelial cells (16HBE) as control." (PMID 33858449, 2021). "The same with the results we have developed from bioinformatics, ALDOA, ENTPD2, LDHA, TYMS were significantly increased in 5 lung cancer cell line, comparing with in 16HBE." (PMID 33858449, 2021). "In this report, we showed that SUN2 decreases glucose uptake, the glycolytic rate and lactate production in lung cancer cells by decreasing the expression of GLUT1 and LDHA." (PMID 26658802, 2015). "The hub gene FAM83A may facilitate lung cancer cell growth by regulating glycolysis via PKM2 and LDHA, offering a novel theoretical foundation and a potential target for prognostic assessment and targeted therapy in LUAD patient." (PMID 41783594, 2026). "LDHA and LDHB subunits play pivotal roles in the metabolic reprogramming of lung cancer cells." (PMID 41154605, 2025). "In lung cancer, DSTYK silencing enhances glycolysis by the Wnt/β-catenin/LDHA axis." (PMID 39220137, 2024). "In lung cancer cell lines, it is reported that lncRNA CRYBG3 regulates glycolysis rather than oxidative phosphorylation to increase lung cancer cell proliferation through interacting with LDHA." (PMID 31850189, 2019). "While LDHA has been extensively studied as a therapeutic target, particularly in cancer, due to its role in the Warburg effect, LDHB remains underexplored, despite its involvement in the metabolic reprogramming of specific cancer types, including breast and lung cancers." (PMID 40733189, 2025). "Furthermore, we also found that PLK1, LDHA, FURIN, FSCN1, and RAB27B were increased in NSCLC cancerous cell lines compared with that in normal human bronchial epithelium cell line BEAS-2B, MS4A1 was down-regulated in lung cancer cells lines." (PMID 37604869, 2023).
lung carcinoma (continued). "Moreover, the lactate content was upregulated in lung cancer cells in which DSTYK expression was disturbed; this upregulation could be restored by knockdown of β-catenin or LDHA expression." (PMID 34853310, 2021). "Here, we discover that lactate dehydrogenase (LDH) B, but not the closely related LDHA, subunits of active LDH with a known function in glycolysis, noncanonically promotes ferroptosis defense in KRAS-driven lung cancer." (PMID 39643712, 2024). "Although LDHA inhibition has not been previously examined, LDHA knockout NSCLC models have decreased tumor formation and even show regression of stablished tumors, providing evidence that LDHA may be a future viable target for lung cancer therapies." (PMID 34745994, 2021).
colorectal cancer (68 papers, 2014 to 2026). A primary or metastatic malignant neoplasm that affects the colon or rectum. "Here, we sought to determine the roles of LDHA expression in aerobic glycolysis in colorectal cancer cells, and identify miRNAs associated with LDHA." (PMID 26062441, 2015). "Previous studies has shown higher levels of LDHA is related with colorectal cancer (CRC), but its role in tumor maintenance and underlying molecular mechanisms has not been established." (PMID 26062441, 2015). "Therefore, this study elucidates the mechanism by which KDM6A regulates glycolysis, and suggests LDHA as a therapeutic target for colorectal cancer carrying KDM6A mutations." (PMID 38840262, 2024). "Additionally, the glycolysis-associated lncRNA of colorectal cancer (GLCC1) promotes metabolic reprogramming of CRC cells through the heat-shock protein 90/cellular myelocytomatosis oncogene/LDHA (HSP90/c-Myc/LDHA) axis." (PMID 36091047, 2022). "In particular, we knocked down LDHA and LDHB to lower histone lactylation levels, and then we restored GDF15 in LDH-deficient colorectal cancer cells." (PMID 40775002, 2025). "To investigate the potential role of histone lactylation in the development of colorectal cancer, we reduced endogenous LDHA and LDHB to lower global lactylation and H3K18 lactylation levels." (PMID 40775002, 2025). "On the contrary, targeted inhibition of METTL3/LDHA axis can improve the sensitivity of colorectal cancer cells to 5-FU in vivo and in vitro." (PMID 38709280, 2024). "Inhibition of LDHA expression induces apoptosis in a variety of tumor cells, such as breast, liver, gastric and colorectal cancers." (PMID 38709280, 2024). "In summary, this study demonstrated that KDM6A promotes the progression of colorectal cancer by upregulating LDHA and glycolysis." (PMID 38840262, 2024). "Colorectal cancer cell lines were chosen because previously we have demonstrated that a genetic inhibition of LDHA and LDHB in LS174T cells impairs the stress response and causes radiation sensitization." (PMID 38229111, 2024). "Curcumin treatment reduces LDHA expression in human colorectal cancer cells, leading to decreased lactate production and cellular proliferation." (PMID 37915411, 2023). "Galloflavin binds to the NADH-binding site in LDHA, inhibiting its ability to bind to single-stranded DNA and suppressing colorectal cancer growth." (PMID 37915411, 2023). "The recruitment of the YTHDF1 protein in an m6A-dependent manner with METTL3 can also promote the translation of LDHA (Lactate dehydrogenase A) mRNA in colorectal cancer." (PMID 38202722, 2023). "In breast and colorectal cancer stem cells, LDHA phosphorylation at Y10 was positively correlated with the progression of metastasis and cell invasion." (PMID 35278714, 2023). "A study on colorectal cells demonstrated that in colorectal cancer cells the AK6 can hyperactivate glycolytic metabolism by phosphorylating lactate dehydrogenase A." (PMID 35712500, 2022). "In short, GLCC1 is the oncogenic lncRNA capable of modulating the interaction between c-Myc and HSP90, and further stabilizing c-Myc protein and regulate glycolytic metabolism via LDHA in colorectal cancer cells." (PMID 31375671, 2019). "There results were consistent with our previous study in colorectal carcinoma, in which we found that NDRG2 inhibited LDHA expression and aerobic glycolysis in colorectal carcinoma by repressing c-Myc expression." (PMID 31523182, 2019). "Koukourakis et al62 found a positive correlation between LDHA expression and distant metastasis of colorectal cancer." (PMID 30403008, 2018). "Overall, our studies demostrate that hCINAP drives colorectal tumour growth and invasion via its adenylate kinase activity by enhancing LDHA Y10 phosphorylation, and provides a potential therapeutic solution in the treatment of colorectal cancer." (PMID 28516914, 2017).
colorectal cancer (continued). "Western blot analysis also showed that the expression levels of LDHA were significantly higher in colorectal cancer tissues (tumor) compared to their matched adjacent normal tissues (normal)." (PMID 26062441, 2015). "We first examined the expression of LDHA in 30 pairs of human colorectal cancer tissues and matched adjacent normal tissues by RT-PCR." (PMID 26062441, 2015). "Higher expression levels of LDHA protein in colorectal cancer tissues were also confirmed by immunohistochemistry." (PMID 26062441, 2015). "Taken together, these results suggested that higher levels LDHA expressed in colorectal cancer tissues plays important roles in cancer progression." (PMID 26062441, 2015). "The majority (19/23, or 82.6%) of colorectal cancer tissues (tumor) exhibited higher expression level of LDHA compared to their matched adjacent normal tissues (normal)." (PMID 26062441, 2015). "More importantly, we identified a genetic loci newly associated with increased colorectal cancer progression, rs18407893 at 11p15.4 (in 3′-UTR of LDHA), which maps to the seed sequence recognized by miR-374a." (PMID 26062441, 2015). "We reported that colorectal cancer express higher levels of LDHA compared with adjacent normal tissue." (PMID 26062441, 2015). "Taken together, these data indicate that LDHA is essential for colorectal cancer cell growth in vitro and in vivo." (PMID 26062441, 2015). "In this study, we uncovered the critical roles of LDHA in aerobic glycolysis in colorectal cancer cells and a mechanism of miRNAs regulated LDHA that contributes to its decreased protein level and activity." (PMID 26062441, 2015). "We demonstrate that LDHA knockdown significantly inhibits cell proliferation in human colorectal cancer cell lines both in vitro and in vivo." (PMID 26062441, 2015). "Importantly, we analyzed the correlation between LDHA expression levels and patient prognosis in colorectal cancer using the TCGA database." (PMID 40113760, 2025). "Moreover, the abundance of glycolysis enzymes (GPI, LDHA) in CHMp exosome was verified with Western blotting, To broaden the scope, we extended to human colorectal cancer-derived exosomes (SW480 vs. SW620) for comparison." (PMID 38419074, 2024). "BHD may predispose patients to colorectal cancer because of folliculin’s role in AMPK/AKT/mTOR signaling and its inhibition of LDHA, synergizing with the more familiar APC pathway through established intermediaries of cell growth." (PMID 36859772, 2023). "In addition, qRT-PCR and IHC staining showed that the expression of LDHA was significantly declined in combination group, establishing that PRMT5 blockade can inhibit the growth of colorectal cancer via the LDHA regulation." (PMID 36474242, 2022). "Another study demonstrated that IGF2BP1 could specifically bind to the 3′-untranslated region (3′-UTR) of lactate dehydrogenase A (LDHA) mRNA, thus leading to enhanced LDHA mRNA stability and facilitation of glycolysis in colorectal cancer cells." (PMID 35918761, 2022). "Furthermore, a previous study found that only 29% of colorectal cancer patients with LDHA overexpression had elevated serum LDH levels." (PMID 34185423, 2021). "It has been reported that high levels of LDHA expression correlated with poor clinical outcome in colorectal cancer, and this gene may regulate glycolytic metabolism, and then promote cancer cell proliferation and invasion." (PMID 31375671, 2019). "In addition, colorectal cancer cell proliferation and glycolytic metabolism were compared after knockdown LDHA and EIF4G2." (PMID 31375671, 2019). "In addition, LDHA was significantly suppressed by NDRG2 in colorectal cancer cells and hepatocellular carcinoma cells." (PMID 31523182, 2019). "It was recently demonstrated that miR-347a directly target LDHA in colorectal cancer cells." (PMID 27458165, 2016). "Colorectal cancer cells with knockdown of LDHA had much slower growth rate than control cells." (PMID 26062441, 2015).
colorectal cancer (continued). "Indeed, LDHA knockdown leads to decreased lactate production and glucose uptake, and decreased in intracellular ATP levels in colorectal cancer cells." (PMID 26062441, 2015). "Furthermore, the function of KDM6A in colorectal cancer also depends on the expression of LDHA." (PMID 38840262, 2024). "The data suggest that GLCC1 may positively regulate LDHA transcription in colorectal cancer cells." (PMID 31375671, 2019). "Also in colorectal cancer, Ji et al47 found that human coilin–interacting nuclear ATPase protein (hCINAP) expression was positively correlated with the level of Y10 phosphorylated LDHA." (PMID 30403008, 2018). "In the context of colorectal cancer (CRC), the G Protein-Coupled Receptor 37 (GPR37) receptor enhances the expression of lactate dehydrogenase A (LDHA) and increases glycolytic activity by activating the Hippo signaling pathway." (PMID 40342932, 2025). "In colorectal cancer, alterations in the tricarboxylic acid (TCA) cycle and overexpression of lactate dehydrogenase A (LDH-A) contribute to lactate accumulation and tumor progression." (PMID 40872698, 2025). "Similarly, in breast and colorectal cancers, B7-H3 exerts comparable effects by inhibiting Nrf2, thereby regulating critical metabolic enzymes such as hypoxia-inducible factor 1-alpha (HIF1α), lactate dehydrogenase A (LDHA), and pyruvate dehydrogenase kinase 1 (PDK1)." (PMID 40214484, 2025). "For instance, in oxaliplatin-resistant colorectal cancer cells, the expression of hexokinase 2 (HK2) and lactate dehydrogenase A (LDHA) is markedly upregulated, thereby enhancing glycolytic flux and reducing intracellular drug accumulation." (PMID 41229498, 2025). "Consistent with this, in our molecular mechanism study, we found that KDM6A regulates LDHA expression by interacting with HIF-1alpha, promoting glycolysis, and subsequently promoting colorectal cancer progression." (PMID 38840262, 2024). "The results showed that Tec downregulated the protein expression of PKM2, HK2, LDHA and GLUT1, which means that Tec is involved in blocking glycolysis in colorectal cancer cells Fig. (1B)." (PMID 38243936, 2024). "In colorectal cancer, several miRNAs, such as miR-34a/c, miR-369-3p, miR-374a, and miR-4524a/b, directly bound the 3′-UTR of the mRNA of LDHA to inhibit the LDHA expression." (PMID 36518315, 2022). "It was also found that LINC00525 knockdown significantly decreased the relative enzymatic activity of LDHA and GLUT1 protein expression in colorectal cancer cells (SW620, SW1116, and LoVo) after being cultured under hypoxia." (PMID 35156520, 2022). "Catalytic enzymes, such as hexokinase 2 (HK2), pyruvate kinase M2 (PKM2), lactate dehydrogenase A (LDHA), and GLUT-1, are markedly inhibited by NDRG2 expression in colorectal cancer cells and patients." (PMID 34685629, 2021). "Consistent with the target molecules inhibited in NDRG2-overexpressing colorectal cancer cells, the expression of GLUT1, glycolytic pathway-related enzymes HK2, PKM2 and LDHA increased significantly in NDRG2-knockdown Caco-2, HT-29 and HCT116 cells." (PMID 26317652, 2015). "Our data demonstrate for the first time that NDRG2 inhibits glycolysis in colorectal cancer cells by inhibiting glucose transporter 1, catalytic enzymes HK2, PKM2, LDHA." (PMID 26317652, 2015). "To verify the relationship between NDRG2 and the target molecules in vivo, we also investigated the expression of NDRG2 and c-Myc, β-catenin, GLUT1, HK2, PKM2, LDHA, ASCT2, GLS1 in tissues from clinical colorectal carcinomas samples." (PMID 26317652, 2015). "Additionally, NAT1 weakens the glycolytic ability of colorectal cancer cells by suppressing the expression of GLUT1 and LDHA." (PMID 38916406, 2024). "RNA sequencing data suggests that NAT1 may regulate liver metastasis of colorectal cancer through the PI3K/AKT/mTOR signaling pathway and inhibits the expression of glycolytic-related metabolic enzymes such as GLUT1 and LDHA." (PMID 38916406, 2024).
colorectal cancer (continued). "A previous study reports that there is no change in LDHA activity in the SIRT5-KO cells of colorectal cancer." (PMID 35278714, 2023). "In a study of clinical samples from colorectal cancer patients, a significant correlation was observed between MYC expression and the expression of multiple metabolic genes, accompanied by elevated LDHB levels, while LDHA levels remained unchanged." (PMID 37915411, 2023). "Moreover, bioinformation analysis demonstrated that higher LDHA (as well as LDHA and PRMT5 combination) indicated a worse prognosis in colorectal cancer patients." (PMID 36474242, 2022). "Here, PRMT5 was found to be upregulated in colorectal cancer and could promote cell proliferation by transcriptionally activating LDHA to enhance aerobic glycolysis, suggesting that PRMT5 may be a potential therapeutic target for colorectal cancer." (PMID 36474242, 2022). "There is a negative correlation between these miRNAs and LDHA expression in colorectal cancer tissues." (PMID 26062441, 2015). "In our results, it was revealed that Tec treatment could effectively inhibit the proliferation of HCT116 colorectal tumor cells, and the expression of PKM2, HK2, LDHA and GLUT1 protein decreased, suggesting that glycolysis might be the promising target of Tec for anti-colorectal cancer therapy." (PMID 38243936, 2024). "In colorectal cancer cells, D-2HG (but not its enantiomer L-2HG, produced from the reduction of α-KG by lactate dehydrogenase A, LDHA, or malate dehydrogenase, MDH) directly induces EMT in colorectal cancer cells by promoting H3K4me3 marks at the ZEB1 promoter and its transcription." (PMID 31277295, 2019). "Furthermore, given that patients with dMMR tumors are likely to respond to treatment with ICIs, LDHA positively regulates MMR protein expression in dMMR and mismatch–repair‐proficient (pMMR) colorectal cancer, while LDHA inhibition can improve the efficacy of ICIs in pMMR colorectal cancer." (PMID 36569893, 2022). "Since the succinylation levels of LDHA did not increase in colorectal cancer, it is speculated that the expression of SIRT5 would not affect the change in LDHA activity." (PMID 35278714, 2023).